TMEM214 (transmembrane protein 214)
Description:
Critical mediator, in cooperation with CASP4, of endoplasmic reticulum-stress induced apoptosis. Required or the activation of CASP4 following endoplasmic reticulum stress.
Synonyms: FLJ20254
Tractability: Antibody: UniProt predicts a signal peptide or a membrane-spanning region. PROTAC: ubiquitination databases record sites on it; its protein half-life has been measured.
Gene: Protein-coding gene on chromosome 2 (27,032,910 to 27,041,697, forward strand). Ensembl gene ENSG00000119777.
Subcellular location: Endoplasmic reticulum membrane
Subcellular location (Human Protein Atlas): Cytosol; Endoplasmic reticulum; Golgi apparatus
Gene Ontology:
Cellular component: cytoplasmic microtubule; endoplasmic reticulum; endoplasmic reticulum membrane
Genetic constraint (gnomAD): Loss-of-function variants: 71 observed, 93.28 expected, observed/expected ratio (o/e) 0.76, 90% interval 0.63 to 0.93. The upper end of that interval is the gene's LOEUF score, 0.93, which puts it in group 3 of 6, group 1 being the genes least tolerant of losing a copy. Missense variants: 754 observed, 855.88 expected, observed/expected ratio (o/e) 0.88, 90% interval 0.83 to 0.94. Synonymous variants: 332 observed, 350.99 expected, observed/expected ratio (o/e) 0.95, 90% interval 0.86 to 1.04.
Homologues: Orthologues: chimpanzee TMEM214 (99% identical), macaque TMEM214 (97% identical), pig TMEM214 (88% identical), rabbit TMEM214 (86% identical), dog TMEM214 (84% identical), rat Tmem214 (82% identical), guinea pig TMEM214 (82% identical), mouse Tmem214 (81% identical), tropical clawed frog tmem214 (55% identical), zebrafish tmem214 (52% identical), Drosophila melanogaster Tmem214 (22% identical).
Diseases named in the same sentence as TMEM214 in open-access papers:
TMEM214 is named in the same sentence as 6 diseases in open-access papers, as found by Europe PMC text mining. Sharing a sentence is not in itself a finding about the gene and the disease. The quoted sentences say what the papers report.
leiomyosarcoma (1 paper, 2020). An uncommon, aggressive malignant smooth muscle neoplasm, usually occurring in post-menopausal women. "By contrast, a LOH of the WT allele of TMEM214 was found in the parietal and peritoneal metastasis of the leiomyosarcoma whereas the data were not informative in the hepatocarcinoma (not shown)." (PMID 33112832, 2020).
myomatous neoplasm (1 paper, 2020). A benign or malignant mesenchymal neoplasm arising from smooth, skeletal, or cardiac muscle. "RIPK3, TFAP2E and TMEM214 were good candidates for the non-neural crest tumors since they are mutated in sarcomas (TCGA SARC), myomatous neoplasms and in hepatocarcinomas (TCGA LIHC) at the somatic level." (PMID 33112832, 2020).
cancer (2 papers, 2018). A tumor composed of atypical neoplastic, often pleomorphic cells that invade other tissues. "Previous studies have shown that the TMEM214 gene was involved in the process of apoptosis in human cells and in signal transduction of cancer cells." (PMID 29899750, 2018). "When running CBaSe on our pan-cancer dataset, five out of nine genes detected as significant by CBaSe were also detected as significant by SSB-dN/dS (BCL2L12, TERT, AP2S1, KRI1, TMEM214)." (PMID 29855388, 2018).
TMEM214 also shares sentences with these, for which no sentence is quoted: essential hypertension (1 paper); sarcoma (1); tendinopathy (1).